HOTAIR (HOX transcript antisense RNA)
Diseases named in the same sentence as HOTAIR in open-access papers (continued):
Sharing a sentence is not in itself a finding about the gene and the disease.
cervical carcinoma (continued). "In conclusion, this study demonstrated that ART effectively inhibited HOTAIR expression, leading to reduction of COX-2 expression and catalytic activity, and finally to the decrease of cervical cancer cell invasion and migration." (PMID 27736969, 2016). "HOTAIR overexpression increased COX-2 expression and PGE2 production in cervical cancer cells treated with ART, while HOTAIR knockdown decreased COX-2 expression and PGE2 production." (PMID 27736969, 2016). "Our results suggest a new model in which HOTAIR sustains reciprocal activation of the PI3K/AKT and Wnt/β-catenin pathways through the HOTAIR/HIF1α axis, thereby contributing to the oncogenic phenotype of cervical cancer." (PMID 39273054, 2024). "The mechanisms underlying the sustained activation of the PI3K/AKT and Wnt/β-catenin pathways mediated by HOTAIR in cervical cancer (CC) have not been extensively described." (PMID 39273054, 2024). "In this study, our results revealed that HOTAIR and miR-214-3p were both differentially expressed in HPV16 positive cervical cancer cells, HOTAIR showed significantly higher expression level, while miR-214-3p remains a lower expression level in cervical cancer cells." (PMID 34320988, 2021). "The results revealed HOTAIR, MALAT1 and MEG3 in cervical cancer patients was higher than that in healthy patients, indicating that lncRNA HOTAIR, MALAT1 and MEG3 levels in the exudates of vaginal lavage fluid samples have the potential of being the biomarkers for early diagnosis of cervical cancer." (PMID 34370713, 2021). "In summary, HOTAIR and miR-214-3p might form a regulated axis and play an important regulation roles in the malignant behavior of HPV16-positive cervical cancer cells." (PMID 34320988, 2021). "HOTAIR could act as a ceRNA through binding to miR-214-3p, promote cell proliferation and inhibit the apoptosis of HPV16 positive cervical cancer." (PMID 34320988, 2021). "In this study, the expression of long non-coding RNA HOTAIR was investigated in HPV16 positive cervical cancer cells, the candidate miRNAs and target genes were identified to clarify putative ceRNAs of HOTAIR/miRNA in cervical cancer cells." (PMID 34320988, 2021). "Taken together, these results suggested that HOTAIR could promote proliferation and inhibit apoptosis in HPV16 positive cervical cancer cells." (PMID 34320988, 2021). "HOTAIR and HIF-1α expression in cervical cancer tissues and cells." (PMID 30355300, 2018). "In the present study, we found that HOTAIR expression was higher in cervical cancer tissues than in corresponding non-cancerous tissues and that it was associated with recurrence in cervical cancer patients." (PMID 25405331, 2015). "HOTAIR expression in cervical cancer tissues was >30-fold that in non-cancerous tissues, suggesting that the expression of HOTAIR is upregulated in cervical cancer." (PMID 25405331, 2015). "As expected, our data suggest that HOTAIR knockdown was dysregulated the expression of EMT-related genes (E-cadherin, β-catenin, Vimentin, Snail and Twist), implying that these genes participate in HOTAIR-induced cervical cancer metastasis." (PMID 25405331, 2015). "The expression level of HOTAIR in cervical cancer tissues was higher than that in corresponding non-cancerous tissues." (PMID 25405331, 2015). "In cervical cancer, a negative correlation existed between miR-29b expression and HOTAIR." (PMID 36430305, 2022). "Oppositely, in HPV16-positive cervical cancer cells, HOTAIR was highly expressed due to the presence of HPV16E7, then miR-214-3p was adsorbed and loses its effect on target genes, and β-catenin expression was released, resulting in malignant phenotype of cervical cancer cells." (PMID 34320988, 2021). "HOTAIR is a negative prognostic factor for breast, liver, colon, pancreatic and cervical cancer." (PMID 25405331, 2015). "Hence, we hypothesized that HOTAIR could be a potential target of E7, in HPV16 related cervical cancers (CaCx)." (PMID 26152361, 2015).
cervical carcinoma (continued). "To further confirm the correlation of HOTAIR and MKL1 and their biological significance in cervical cancer patient, we detected the expression level of HOTAIR and MKL1 in a TMA II containing 31 informative patients with cervical cancer tissues and their corresponding adjacent non-cancer tissues." (PMID 29391067, 2018).
colorectal cancer (95 papers, 2013 to 2025). A primary or metastatic malignant neoplasm that affects the colon or rectum. "Previous studies have shown that HOTAIR, a related lncRNA, is associated with multiple cancers, including head and neck, ovarian, gastric, hepatic, colorectal cancers, and glioblastoma." (PMID 40746924, 2025). "HOTAIR expression is increased in colorectal cancers and is associated with metastasis and poor prognosis." (PMID 38473243, 2024). "Bioinformatics data indicated that HOTAIR was overexpressed in most of these human malignancies and was significantly associated with the prognosis of patients with cancer, especially in colorectal cancer (CRC)." (PMID 38696320, 2024). "In colorectal cancer, studies have documented that HOTAIR expression in tumor tissue was higher than that in normal tissue, and upregulated HOTAIR was associated with poor clinical prognosis." (PMID 35798695, 2022). "The current study examined the HOTAIR gene rs1899663 G>T polymorphism in 100 patients with colorectal cancer and 93 healthy persons by a real-time polymerase chain reaction." (PMID 35946893, 2022). "This research is the first to demonstrate the relationship between colorectal cancer and the HOTAIR gene rs1899663 polymorphism in the Turkish population, which is a Caucasian population." (PMID 35946893, 2022). "For example, lncRNA HOTAIR has been reported to associate with liver metastases of colorectal cancers." (PMID 34307387, 2021). "For example, HOTAIR regulates polycomb-dependent chromatin modification and is associated with poor prognosis in colorectal cancers." (PMID 28881797, 2017). "HOTAIR expression from patients diagnosed with stage IV colorectal cancer (CRC) was demonstrated to associated with poor prognosis." (PMID 27911863, 2017). "The results suggested that high levels of HOTAIR may be linked to the advancement of colorectal cancer in both patients and cell lines." (PMID 40072116, 2025). "HOTAIR is an oncogenic RNA whose expression level is associated with many clinical features such as tumor grade and prognosis and has been explored to be oncogenic in colorectal cancer (CRC)." (PMID 38696320, 2024). "In addition, the association between HOTAIR gene polymorphisms and colorectal cancer prevalence, including the altered expression patterns of HOTAIR polymorphisms, were reported for the first time." (PMID 32117729, 2020). "For example, lncRNA HOTAIR levels are elevated in many types of cancer, including primary and metastatic breast cancer, colorectal carcinoma and gastrointestinal stromal cancer, and in most cases, high HOTAIR expression is associated with poor patient survival." (PMID 29137343, 2017). "HOTAIR has been widely identified to participate in tumor pathogenesis, acting as a promoter in colorectal cancer carcinogenesis, and rs7958904 CC decreased the risk of colorectal cancer compared with GG genotype." (PMID 26967566, 2016). "In recent studies, there are some reports indicating the role of HOTAIR SNPs which make it a significant cancer susceptibility locus and provide high risk for some cancers, like breast, gastric, cervical, papillary thyroid carcinoma, osteosarcoma, prostate, ovarian, and colorectal cancers." (PMID 30873206, 2019). "On the other hand, in colorectal cancer lines, qPCR analysis corroborated the increase in HOTAIR expression in tumor cells (RKO, HCT-116, and SW-620) compared to non-tumor cells (CRL-1459)." (PMID 40072116, 2025). "Our initial analysis, utilizing data from The Cancer Genome Atlas (TCGA), revealed that HOTAIR is overexpressed in samples from patients with colorectal cancer and its expression increases with tumor stage." (PMID 40072116, 2025). "In terms of metabolism, HOTAIR can regulate the expression of enzymes related to glycolysis and glutaminolysis in colorectal cancer cells, such as PFKFB4, PGK1, and LDHA, directly impacting the production of lactate and glutamate." (PMID 41311582, 2025).
colorectal cancer (continued). "HOTAIR is involved in the modulation of glycolysis and glutaminolysis within colorectal cancer cells." (PMID 41311582, 2025). "In this study, we used a differential expression model of HOTAIR in colorectal cancer cells to evaluate the role of this lncRNA in metabolic reprogramming and its potential interaction with HIF-1α." (PMID 40072116, 2025). "Further, glutamate production was regulated proportionally to HOTAIR expression in the three colorectal cancer lines, where overexpression of the lncRNA increased glutamate production and silencing promoted the inverse effect." (PMID 40072116, 2025). "HOTAIR influences the metabolic pathways of colorectal cancer cells by regulating the expression of enzymes tied to glycolysis and glutaminolysis." (PMID 41311582, 2025). "In colorectal cancer, for example, lncRNA HOTAIR functions as a sponge for miR-206 and frees CCL2 mRNA from being impacted by miR-206." (PMID 41154428, 2025). "By observing the discrepancies between the different colorectal cancer cell lines, we considered that the enzymes that were affected by both HOTAIR overexpression and inhibition in at least two of the three lines evaluated would be considered HOTAIR targets." (PMID 40072116, 2025). "To further explore the mechanism of how HOTAIR regulates colorectal cancer proliferation and migration, we performed an RNA sequencing analysis." (PMID 38696320, 2024). "Specific lncRNAs, such as MALAT-1, HOTAIR, LINC00152, and others, have shown diagnostic potential in prostate, lung, colorectal, hepatocellular, gastric, renal, and colorectal cancers." (PMID 39132504, 2024). "Several studies reported that certain lncRNAs contribute to the progression of colorectal cancer, such as HOTAIR, MALAT-1, and CCAT1/CCAT2." (PMID 38473243, 2024). "For example, HOTAIR contributes to 5FU Resistance through suppressing miR-218 and activating NF-κB/TS signaling in colorectal cancer." (PMID 38696320, 2024). "For example, lncRNA HOTAIR contributes to colorectal cancer and 5-FU resistance through the recruitment of EZH2 and subsequent silencing of miR-218, upregulation of VOPP1 expression and subsequent activation of the NF-κB/TS pathway." (PMID 37680988, 2023). "They used colorectal cancer tissues and cells to find the potential downstream signalling pathways of HOTAIR, which leads to the different results." (PMID 37621132, 2023). "SNPs in the HOX Transcript Antisense RNA (HOTAIR) gene, which is an oncogene that regulates gene expression and chromatin dynamics, have been associated with breast and colorectal cancers." (PMID 37189693, 2023). "On the other hand, HOTAIR depletion has also been demonstrated to inhibit cell autophagy in colorectal cancer due to its miR-93 sponging capacity, which regulates ATG12 expression." (PMID 35309939, 2022). "HOTAIR knockdown and miR-203a-3p upregulation in colorectal cancer cell lines leads to lowered Wnt/β-catenin signaling, cell proliferation, and reduced chemoresistance." (PMID 35309939, 2022). "We first evaluated expression levels of several lncRNAs in eight excised liver metastases from primary colorectal cancers and found significantly upregulated lncRNAs HOTAIR and MALAT1 along with significantly downregulated LOC285194." (PMID 34307387, 2021). "Recently, investigations on colorectal cancer revealed that HOTAIR targets Wnt/β-Catenin pathway by sponging miR-203-3p, while presence of this microRNA can cause cell sensitivity to Cisplatin and Paclitaxel by blocking Wnt/β-Catenin pathway." (PMID 32245498, 2020). "It is of noted that CC genotypes of HOTAIR rs7958904 has been reported to be associated with decreased osteosarcoma, EOC, and colorectal cancers risk." (PMID 30873206, 2019). "It has been shown that overexpression of HOTAIR contributed to the invasion and metastasis of several cancer cells, such as hepatocellular cancer, pancreatic carcinoma, breast cancer and colorectal cancer." (PMID 30355300, 2018).
colorectal cancer (continued). "Higher level of HOTAIR was also found in colorectal cancer tissues comparing to that in the adjacent tissues, closely related to the patients’ age, clinical stages, invasive depth and lymphatic metastasis." (PMID 30355300, 2018). "Other important lncRNAs, such as HOTAIR and CCAT2 have been showed that they have played critical roles in the development of colorectal cancers and are associated with poor prognosis in CRC." (PMID 29340086, 2017). "Many studies have demonstrated that HOTAIR is overexpressed in many cancers, such as breast, gastric and colorectal cancers." (PMID 28177890, 2017). "For instance, HOTAIR expression was upregulated in tumor tissues of colorectal cancer (CRC) patients, and HOTAIR knockdown inhibited proliferation, migration and invasiveness while enhanced apoptosis and radiosensitivity of CRC cells." (PMID 28376901, 2017). "HOTAIR has been shown to affect migration and invasion in breast, gastric, esophageal and colorectal cancers." (PMID 26800519, 2016). "Several studies have shown that HOTAIR is dysregulated in many cancers, including colorectal carcinomas." (PMID 27148353, 2016). "Nowadays, biological experiments have further linked mutations and dysregulations of some lncRNAs with the development and progression of colorectal cancer, such as HOTAIR, KCNQ1OT1, and MALAT1 in our training samples." (PMID 26061969, 2015). "In these thousands of lncRNAs, HOTAIR is a star that is highly expressed in primary breast tumors, hepatocellular carcinoma, colorectal cancer and gastrointestinal stromal tumors." (PMID 25928008, 2015). "For example, MALAT1 has been detected in the blood of patients with non-small cell lung cancer, and HOTAIR in colorectal cancer patients." (PMID 26516918, 2015). "Studies have associated the aberrant expression of lncRNAs with the tumor progression or metastasis, for example, PCAT-1 and SChLAP1 in prostate cancer, HOTAIR in breast and colorectal cancer." (PMID 26158411, 2015). "HOTAIR overexpression is observed in colorectal carcinomas with advanced stage and liver metastases." (PMID 26448935, 2015). "Some studies reported that up-regulation of HOTAIR contributes to tumorigenesis, including bladder cancer, cervical cancer, colorectal cancer, etc., while a few evidences exhibited an adverse effect recognized as a protective factor to against carcinogenesis." (PMID 25303230, 2014). "Conversely, siRNA-induced knockdown of HOTAIR decreased cell invasion (p < 0.05), further suggesting that HOTAIR is related to liver metastases and is a potential prognostic factor in colorectal cancer." (PMID 25334066, 2014). "Inhibition of HOTAIR reduced 5-FU resistance in colorectal cancer (CRC) via miR-218/VOPP1 axis." (PMID 40949794, 2025). "Therefore, to corroborate this effect on the expression of glucose and glutamine metabolism enzymes, we generated a differential expression model of HOTAIR in colorectal cancer lines." (PMID 40072116, 2025). "Furthermore, HOTAIR promoted oxaliplatin resistance and EMT in colorectal cancer via negative regulation of miR-1277-5p and knockdown of HOTAIR significantly upregulated miR-1277-5p expression, increasing chemosensivity through inhibition of ZEB1 expression." (PMID 40176927, 2024). "In addition, lncRNA HOTAIR was engaged in cellular metastasis in various cancers, such as colorectal cancer, hepatocellular cancer, and non-small-cell lung cancer." (PMID 38561760, 2024). "HOTAIR accelerates colorectal cancer progression via the PI3K/AKT/mTOR pathway." (PMID 35248107, 2022). "Similar results indicated that the HOTAIR level was associated with genome-wide reprogramming of PRC2 function and that HOTAIR upregulation could be a key factor in the progression of colorectal cancer (CRC) metastasis." (PMID 36100611, 2022). "In addition, HOTAIR has been reported to be aberrantly expressed in several tumors, including cervical cancer, colorectal cancers, gastric cancer, breast cancer, and hepatic carcinoma." (PMID 32462038, 2020).